EGFR (epidermal growth factor receptor)
Diseases named in the same sentence as EGFR in open-access papers (continued):
Sharing a sentence is not in itself a finding about the gene and the disease.
lung cancer (continued). "To further explore whether tumor regression, and not erlotinib directly, was causing the observed changes in the immune microenvironment, we studied mice with EGFR mutant lung cancer induced by expression of the EGFRL858R + T790M mutant that is unresponsive to erlotinib treatment." (PMID 31291990, 2019). "There was a significantly higher proportion of EGFR mutation in patients with family history of lung cancer (FHLC) than those without (OR = 1.53[1.18–1.99], P = 0.001), including in analyses limited to those who had lung cancer in their first degree relatives (OR = 1.76 [1.36–2.28], P < 0.0001)." (PMID 31703574, 2019). "Interestingly, in this case no mutations in the most frequent lung cancer driver genes, namely EGFR, KRAS, AKT and ROS1 were present in the tumor sample, and neither was the EML4-ALK fusion gene." (PMID 30744199, 2019). "Reducing drug acquisition costs may improve access to EGFR-targeted therapy for lung cancer." (PMID 32159636, 2019). "In addition, it was shown that the frequency of EGFR mutations is also higher in women, nonsmokers, and patients with adenocarcinoma, as compared to other types of lung cancer." (PMID 30406002, 2018). "Despite our promising findings with platinum-based therapies and EGFR inhibitors, there is still a high percentage of patients who may not respond to these therapies, highlighting the necessity for novel therapies in lung cancer." (PMID 30119639, 2018). "However, EGFR-activating mutations that confer proven sensitivity to tyrosine kinase inhibitors (TKIs) in lung cancer have not yet been reported in GBM." (PMID 30305059, 2018). "We also tested whether B[α]P or NNK can affect the sensitivity of lung cancer cells to EGFR TKIs." (PMID 29570930, 2018). "Long-term exposure of lung cancer cells to EGFR-TKIs may lead to accumulation of ANKRD1 protein." (PMID 30291293, 2018). "Over the last decade, clinical management and treatment of lung cancer patients has become more dependent on molecular classification using “driver” mutations that occur in genes, such as anaplastic lymphoma kinase (ALK), epidermal growth factor receptor (EGFR), and c-Ros oncogene 1 (ROS1)." (PMID 29300322, 2018). "Thus, EGFR has become an important therapeutic target for lung cancer treatment." (PMID 29348400, 2018). "The total incidences in Korea are not significantly different from other countries, but the incidence of lung cancer is higher in non-smokers and women in Korea, and epidermal growth factor receptor (EGFR) mutations are detected much more frequently than in Western countries." (PMID 30522449, 2018). "Moreover, some miRNA are known to regulate EGFR pathway in lung cancer and may affect EGFR-TKIs sensitivity as well as patients’ outcome." (PMID 29689091, 2018). "Moreover, in EGFR-driven lung cancer and CRC, MET activation is a very common cause of resistance to anti-EGFR drugs, so that the use of MET inhibitors could possibly overcome this resistance." (PMID 30441809, 2018). "Indeed, we acknowledge that sensitizing EGFR mutations are not commonly found in SCC lung cancers, and that these mutations are the strongest predictors of response to EGFR tyrosine kinase therapy." (PMID 29581842, 2018). "Therefore, understanding EGFR-regulated signaling pathways or cross-talk of other molecular mechanisms with EGFR signaling pathways may provide a way to treat or prevent lung cancer." (PMID 29548337, 2018). "Finally, our results strongly indicated the EGFR activation could specifically induce the expression of SALL4 in lung cancer and also suggest a positive association between SALL4 expression and EGFR mutation." (PMID 29691367, 2018). "Additionally, by using cBioPortal for Cancer Genomics database, we have found a reduction in median months of survival in lung cancer patients that exhibit an upregulation of a nuclear EGFR gene signature, thus showing a trend between nuclear EGFR and poor prognosis in NSCLC." (PMID 29599917, 2018).
lung cancer (continued). "In fact, with increasing understanding of the high rates of epidermal growth factor receptor (EGFR) mutated lung cancer in non-smoking Asian and Hispanic women, it is clear that the etiology of this subtype of lung cancer is quite different than the more common smoking-associated subtypes." (PMID 29791458, 2018). "Whether this is also true for patients with EGFR-mutated lung cancer is not clear, neither is the underlying molecular mechanisms." (PMID 29484139, 2018). "Those minimal invasive examinations have significantly improved lung cancer diagnosis; however, small samples and cytologic specimens were sometimes not sufficient of quality or quantity for EGFR mutation testing in which the reported failure rates are about 5% to 30%." (PMID 29164298, 2018). "Preclinical studies, including ours, have revealed that lung cancer cells easily acquire resistance to 3rd-gen EGFR-TKIs in vitro, and some resistant cells could be clinically un-targetable, which may narrow the long-term clinical benefits of EGFR-TKIs." (PMID 29386539, 2018). "However, it remains unknown whether and how cigarette smoke influences the sensitivity to EGFR TKIs in lung cancer." (PMID 29570930, 2018). "Therefore, a more detailed understanding of EGFR biology in lung carcinomas is required." (PMID 29950164, 2018). "Always in lung cancer cells, Dasatinib sensitivity was not correlated with c-Src level but could be associated with the presence of EGFR-activating mutations." (PMID 28446239, 2017). "In addition, we checked EGFR status and found that Derlin-1 overexpression could upregulate EGFR phosphorylation, which was in accord with our previous findings in lung cancer." (PMID 28178653, 2017). "Furthermore, statins can overcome EGFR-TKI resistance in lung cancer cells and patients." (PMID 28158206, 2017). "Therefore, we suggest that the use of MnO2 NPs in combination with radiotherapy may be an effective strategy for the treatment of EGFR-TKI-resistant lung cancers in normoxic and hypoxic conditions." (PMID 29255705, 2017). "Going forward, in lung cancer, EGFR may be the rising star in the era of precision medicine." (PMID 28430586, 2017). "Therefore, aberrant EGFR activation becomes a target for the design of novel lung cancer treatment." (PMID 29312591, 2017). "CAR intergenic 10 (CAR10) a novel lncRNA, could bind and stabilize transcription factor Y-box-binding protein 1 (YB-1), leading to up-regulation of the epidermal growth factor receptor (EGFR) and proliferation of lung cancer cells, and CAR10-YB-1 represented a potential therapeutic target in NSCLC." (PMID 27992369, 2017). "Similar effects were seen with siRNA-GLI1 or a mixture of siRNA-MEOX2 plus siRNA-GLI1, but no significant reduction in cellular viability occurred with either anti-MEOX2 or anti-GLI-1 siRNAs in an EGFR-mutated lung cancer cell line H1975 with non-detectable MEOX2 mRNA expression." (PMID 28978016, 2017). "Due to the high efficacy levels of the combination of bortezomib and EGFR inhibition in the LC cell lines in our study we believe that further studies of this combination are warranted in order to establish its potential as a new treatment option for lung cancer." (PMID 29096687, 2017). "However, the effect of statin use in patients with lung cancer receiving EGFR-TKI therapy remains unclear." (PMID 28158206, 2017). "As ErbB3 is essential for growth of EGFR-mutated lung cancer cells, the ZEB1/miR-200 negative feedback loop might potentially provide a cell context-dependent regulation of ErbB3." (PMID 28587302, 2017). "Additionally, miRNAs could also be employed as novel therapeutic targets to circumvent the resistance of lung cancer cells to EGFR inhibitors, and as biomarkers for response to anti-EGFR agents." (PMID 28430586, 2017).
lung cancer (continued). "Furthermore, to validate that G9a regulates the stemness property in lung cancer and understand whether it downregulates EGFR signaling in lung cancer cells, UNC0642 was co-treated with or without EGF in HCC827 cells." (PMID 28787001, 2017). "Furthermore, immunoblotting was performed to determine whether the sensitivity of lung cancer cells to EGFR-TKIs was mediated through inhibition of EGFR signaling." (PMID 29285266, 2017). "Therefore, CK2 may be an attractive candidate for developing a novel therapeutic strategy for EGFR-TKI resistance lung cancer." (PMID 28290473, 2017). "Median survival in patients with advanced lung cancer is usually 1 year or less, and patients with epidermal growth factor receptor (EGFR)-mutant metastatic non-small-cell lung cancer (NSCLC) may have longer overall survival (OS) when treated with tyrosine kinase inhibitors (TKIs)." (PMID 28591157, 2017). "In 2013 International association for lung cancer research (IASLC) amended and supplemented the Martini-Melamed criteria, by multidisciplinary classification of lung adenocarcinoma, epidermal growth factor receptor (EGFR), K-ras added for differential diagnosis." (PMID 29277187, 2017). "Therefore, our study demonstrated that miR-107-5p not only suppressed the progression in NSCLC cells by inhibiting the expression of EGFR, but also could be a promising and a new potential therapeutic target for lung cancer." (PMID 28915650, 2017). "Recently, it has been reported that combined inhibition of EGFR-TKIs (erlotinib) and TGF-β type I receptor inhibitor may improve sensitivity of EGFR-TKIs in lung cancer without EGFR T790M mutation." (PMID 28288164, 2017). "Although osimertinib is very effective in lung cancer patients with the secondary EGFR mutation, the other 50% of patients who do not develop the T790M mutation receive platinum-based chemotherapy as their second-line treatment, and the prognosis of these patients is poor." (PMID 28683123, 2017). "For target-based therapy of lung cancer, gefitinib, as the first generation of tyrosine kinase inhibitors (TKIs), demonstrated good initial response to the non-small cell lung cancer (NSCLC) patients whom harbors epidermal growth factor receptor (EGFR) mutation." (PMID 29221189, 2017). "G9a can maintain CSC characteristics in head and neck squamous cell carcinoma; therefore, we investigated whether G9a is generated as the downstream protein of EGFR in EGFR-positive lung tumor cells, for determining the stemness property in EGFR-positive lung cancer." (PMID 28787001, 2017). "In addition to the current cornerstones of targeted therapy in NSCLC, EGFR mutations and ALK gene fusions, a growing number of alterations, like ROS1 gene fusions, are emerging as treatment predictive in lung cancer broadening the cohort of patients eligible for targeted treatment." (PMID 28415793, 2017). "Therefore, studies of the mechanisms underpinning the resistance toward anti-EGFR agents may afford important findings for the use of anti-EGFR therapies in lung cancer treatment." (PMID 28430586, 2017). "This implies that some lung cancers may depend on wt-EGFR expression for maintenance." (PMID 26646697, 2016). "Although EGFR inhibitor, an effective therapy for EGFR driven lung cancer, has been shown to down-modulate PD-L1 on lung cancer cell lines in our study and other reports, whether it leads to better T cell mediated tumor killing has not been clearly demonstrated." (PMID 27467256, 2016). "Determining whether 1αOHase is required for 25D3-mediated activity advances the clinical potential of dietary vitamin D3 supplementation because CYP27B1 expression is significantly decreased in EGFR mutant lung cancer cells under pressure of erlotinib treatment both in vitro and in vivo." (PMID 26654942, 2016). "We next examined whether TOPK directly affected the sensitivity of lung cancer cells to EGFR-TKIs." (PMID 26745678, 2016).
lung cancer (continued). "Moreover, blockade of IL-8 could render erlotinib-resistant lung cancer cells more amenable to EGFR inhibition or chemotherapy." (PMID 27248176, 2016). "Thus, it might be intriguing to see if GA would effectively increase therapeutic potential of TKI in EGFR lung cancer." (PMID 27419630, 2016). "As EGFR activation induces downstream signaling pathways driving tumor proliferation and/or anti-apoptosis, targeting activated EGFR signaling by using TKIs such as gefitinib or erlotinib markedly suppresses tumor growth, leading to remarkable clinical benefit for lung cancer patients." (PMID 27419630, 2016). "Our IHC experiments indicated that EGFR-mutated lung cancers were associated with higher YAP1 activation, thus YAP1-targeted therapy may potentiate the cytotoxicity of erlotinib (tyrosine kinase inhibitor targeting EGFR) in EGFR-mutated NSCLC cells." (PMID 26716514, 2016). "But so far, general method for detecting EGFR mutations in lung cancer is direct sequencing with a low sensitivity, which could not uncover the EGFR gene status of tumor factually." (PMID 27489355, 2016). "While many of the multi-acting compounds were members of scaffold D, which generally looked cytotoxic, EGFR inhibitors based on this scaffold have been patented as possible lung cancer drugs, so clinically safe compounds based on scaffolds like this one may be possible." (PMID 26934697, 2016). "Although EGFR mutations in SACC are not as high as in lung cancer, the clinical effectiveness of targeting EGFR in SACC suggests that a different mechanism may be involved." (PMID 26958807, 2016). "It is therefore interesting that early‐phase clinical trials involving vaccines against T in patients with lung cancer and chordoma are showing some evidence of clinical activity 79, 80, 81, and it would be of interest to know whether p‐EGFR is suppressed in the clinical samples from these patients." (PMID 27102572, 2016). "Moreover, we wished to test whether osimertinib resistance led to an altered metabolic phenotype, and critically, whether OxPhos inhibition could inhibit the development of osimertinib resistance in EGFR mutant lung cancer lines." (PMID 27861144, 2016). "Therefore, we measured the frequency of EGFR T790M in an EGFR-mutant lung cancer cell line resistant to EGFR-TKIs, which were established using two different drug-treatment regimens, in order to determine the relevance of these regimens to the emergence of clinically relevant drug resistance." (PMID 27270313, 2016). "Mutation in PIK3CA signaling pathways may induce resistance to EGFR‐TKIs of lung cancer patients." (PMID 27554588, 2016). "Furthermore, the intermittent drug treatment was less effectively induced the emergence of the EGFR T790M mutation which is the most common resistance mechanism found in EGFR-mutant lung cancer patients treated by EGFR-TKI, compared with the continuous drug treatment." (PMID 27270313, 2016). "The results of this study suggest that combined use of EGFR-TKI and MET inhibitors or inhibition of downstream signaling molecules, such as PI3K or MEK, might be a better second or third-line strategy for a group of patients with advanced lung cancer harboring wild-type EGFR." (PMID 26919104, 2016). "This means that ERK1/2 may also be involved in driving EGFR-TKI resistance in lung cancer." (PMID 26745678, 2016). "Therefore, more effective therapeutics are needed for lung cancer patients, particularly for the ones that are negative for EGFR mutations." (PMID 27705911, 2016). "As depletion of NOTCH1 promotes ERBB3 in cells harbouring various gene mutations, such a NOTCH1–ERBB3 axis may be widely present in lung cancer cells and serve as a common signalling mechanism that regulates the growth of ERBB3-dependent cells, especially EGFR-mutated cells." (PMID 27456471, 2016).
lung cancer (continued). "In conclusion, lung cancer in young patients (≦ 45 year-old) was associated with unique characteristics, with greater percentages of female patients, adenocarcinoma, and never-smokers and a lower EGFR mutation rate compared with older patients." (PMID 27191886, 2016). "Therefore, targeting EGFR during the early stage of lung tumorigenesis could suppress the development of lung cancer." (PMID 27458163, 2016). "Similarly, endogenous TOPK co-immunoprecipitated with c-Jun in A549 cells, suggesting that the two proteins could form a complex in EGFR-TKI-resistant lung cancer cells." (PMID 26745678, 2016). "Therefore, we suggest that the distribution of EGFR mutation subtypes among lung cancer families was random, rather than showing a pattern of familial aggregation." (PMID 27449093, 2016). "Importantly, we have also observed positive SALL4 expression in EGFR mutation negative lung cancer patients." (PMID 27705911, 2016). "In agreement with those previous reports, we have demonstrated here a robust increase of IL-8 secretion and upregulation of CXCR1 in erlotinib-resistant lung cancer cells, compared to their parental counterparts, regardless of the mutational status of EGFR or KRAS." (PMID 27248176, 2016). "We found that IL10 was increased in Kras4bG12D- and EGFRL858R-induced lung cancer mice, which is consistent with the results in lung cancer patients and indicates that Kras and EGFR activation are involved in IL10 expression and might be positively related to lung cancer formation." (PMID 26956044, 2016). "Thus, our data suggests that YAP1 may be a common modulator of resistance mechanisms to platinum, radiation and EGFR-targeted therapies in lung cancer." (PMID 26716514, 2016). "Interestingly, according to the results of this study, we found the gefitinib failed to suppress the activation of PI3K/AKT pathway in the lung cancer stem cells in vitro and in vivo, whereas the EGFR signaling could be inhibited by this kind of EGFR-TKI." (PMID 27690301, 2016). "To demonstrate the effectiveness of the CTODC’s collective database infrastructure and its data sharing capabilities, we conducted a proof of principle investigation of patients with lung cancer with and without EGFR mutations who had taken erlotinib at the three institutions mentioned previously." (PMID 27092293, 2016). "In conclusion, our findings demonstrated that lung cancer in younger patients (≦ 45 years) has unique characteristics, with a greater proportion of female patients, adenocarcinoma, and never-smokers, and a lower EGFR mutation rate compared with older patients." (PMID 27191886, 2016). "Moreover, conjugated nanoparticles could activate and induce the internalization of overexpressed Epidermal Growth Factor Receptor in human lung carcinoma cells." (PMID 27788212, 2016). "Interestingly, combination therapy with c-Met and EGFR inhibitors in lung cancer are positive." (PMID 26000702, 2015). "The low prevalence of EGFR mutations among COPD patients without a smoking history suggests that NSCLC presenting with COPD may be a separate phenotype of lung cancer." (PMID 26555338, 2015). "Therefore, studies of the mechanisms underpinning the resistance toward anti-EGFR agents may provide important findings for lung cancer treatment using anti-EGFR therapies." (PMID 26273639, 2015). "Therefore, it appears unlikely that EGFR signaling mediates C/EBPβ activity in lung cancer cells." (PMID 25767874, 2015). "However, there are insufficient data on how MET- or AXL-mediated resistance to EGFR-TKI in lung cancer could be overcome by inhibiting HSP90." (PMID 25780909, 2015). "Since no survival gain was demonstrated in the phase III trials conducted so far, the use of EGFR TKIs in EGFR-mutated patients in first- or second-line should not influence the eventual survival outcome, as demonstrated in the phase II trial of the Spanish Lung Cancer Group." (PMID 26308162, 2015).